EGFL6 (EGF like domain multiple 6)
Diseases named in the same sentence as EGFL6 in open-access papers (continued):
Sharing a sentence is not in itself a finding about the gene and the disease.
tumor (continued). "Additionally, the tumor targeting and SPECT imaging properties of the EGFL6 peptide were investigated in vivo." (PMID 26045973, 2014). "Thus, EGFL6 and EGFL7 had a similar performance in tumor immunity and micro-environment." (PMID 33391349, 2020). "Since EGFL6 is highly expressed in tumor vessels but does not affect the normal wound healing, researchers have proposed EGFL6 as a new target for targeted inhibition of tumor vessels." (PMID 32624687, 2020). "Given that Egfl6 enhanced the expression of PD-L1 on tumor-infiltrating myeloid cells and inhibited the response to ICI therapy, we reasoned that targeting tumor-derived Egfl6 might reverse the immunosuppressive TME and restore the efficacy of a-PD-L1 treatment in a 2F8c tumor model." (PMID 39312740, 2024).
cancer (11 papers, 2014 to 2025). A tumor composed of atypical neoplastic, often pleomorphic cells that invade other tissues. "Epidermal growth factor-like domain 6 (EGFL6) has been reported to be associated with cancer development." (PMID 33726836, 2021). "We then performed a survival analysis to determine the association between EGFL6, −7, and −8 and cancers." (PMID 33391349, 2020). "We then further assessed the association between the expression of EGFL members and patient’s overall survival in 33 cancer types and found that the results varied in different cancer types, but EGFL6 and EGFL7 were mainly associated with poor prognosis." (PMID 33391349, 2020). "EGFL6 also promotes both endothelial cell migration during angiogenesis and cancer cell migration to drive cancer metastasis." (PMID 39312740, 2024). "In cancer and in development, EGFL6 regulates differentiation of many cell types in a paracrine and autocrine manner, including osteoblasts, cancer stem-like cells, and adipocytes." (PMID 39312740, 2024). "Our group and others have previously reported the ability of EGFL6 to promote ovarian tumorigenesis by increasing angiogenesis, stimulating cancer cell asymmetric division and inducing migration and cancer cell metastasis." (PMID 39312740, 2024). "Consistent with the finding in migration assay, EGFL6 siRNA treated cancer cells reaching the lower matrigel-free well was significantly reduced in comparison with scrambled siRNA-treated groups." (PMID 33726836, 2021). "Since cell migration and invasion are critical properties for the dissemination of cancer cells and metastasis; therefore, in vitro migration and invasion assays were performed to investigate the effect of EGFL6 on cell invasiveness." (PMID 33726836, 2021). "This also suggests the potential role of EGFL6 in regulating cancer cell migration under hypoxia condition." (PMID 33726836, 2021). "Regardless of the subtypes and differentiation status of the cancers, EGFL6 was overexpressed in all four patients with malignant ovarian cancers, while the normal ovarian tissue showed minimal EGFL6 expression." (PMID 32983976, 2020). "The study of EGFL6 in various tumors shows that EGFL6 plays an important role in the occurrence and development of cancer." (PMID 32624687, 2020). "EGFL6 had the highest correlation with the stromal score among all cancer types (r = 0.71, P < 0.001), following with EGFL7 (r = 0.65, P < 0.001) and EGFL8 (r = 0.19, P < 0.001)." (PMID 33391349, 2020). "The univariate Cox proportional hazard regression model showed that EGFL6 and EGFL7 were the risk factors to predict poor prognosis of cancers." (PMID 33391349, 2020). "Simultaneously, EGFL6, −7, and −8 signals were verified as promising targets for cancer therapies, although further laboratory validation is still required." (PMID 33391349, 2020). "The expression levels of EGFL8 were relatively lower among all cancer types than that of EGFL6 and EGFL7, with EGFL7 having the highest level of expression." (PMID 33391349, 2020). "In order to understand the intrinsic expression pattern of EGFL genes, the expression degrees of EGFL6, 7, and 8 were determined in 33 types of cancers, which are available in TCGA pan-cancer data." (PMID 33391349, 2020). "Epidermal growth factor‐like domain multiple 6 (EGFL6) is a secreted protein, regulates maintenance and metastasis of cancer cells." (PMID 30444069, 2018). "Taken together, we found that EGFL6 could regulate cancer cell migration, invasion, proliferation and self-renewal by affecting EGFR and integrin receptor signaling." (PMID 33726836, 2021). "In addition, matrix metalloproteinase (MMP), ADAMTS1 and Snail are factors associated with cancer migration and invasion; thus, we analyzed MMP-2, MMP-9, ADAMTS1, and Snail expressions in EGFL6 siRNA treated HCT116 and HT29." (PMID 33726836, 2021).
cancer (continued). "In addition, the expression of EGFL6 in the vascular endothelium is related to the increase of metastasis of cancer cells and primary cancer cells." (PMID 32624687, 2020). "The pattern of the association between the gene expression of EGFL6 and eight and immune subtypes in CRC was similar to that observed in the use of all 33 TCGA tumors in all cancer types; EGFL6 was significantly associated with immune infiltrate types (P < 0.001)." (PMID 33391349, 2020). "In conclusion, EGFL6, 7, and 8 are more likely to offer a breakthrough for cancer therapy." (PMID 33391349, 2020). "Therefore, EGFL6 gene products represent potential markers of malignant tumors 15 and are candidate targets for small molecule or antibody therapeutic agents for treating certain tumors." (PMID 32624687, 2020). "EGFL6 is expressed at higher levels in embryos and various malignant tumors than in normal tissues." (PMID 32624687, 2020). "In addition, EGFL6, −7, and −8 were more likely to contribute to the resistance of cancer cells." (PMID 33391349, 2020). "Thus, the expression of EGFL6 in tumors suggests that it may also be related to the occurrence and development of cancer 29,30,39-43." (PMID 32624687, 2020). "The in vitro studies proffered evidence that under hypoxia condition, EGFL6 binds to EGFR, activates EGFR/αvβ3 integrin receptors to affect cancer cell proliferation." (PMID 33726836, 2021). "From the results in this research, EGFL6 regulates STAT3, FAK and Src, which correlate to cancer stem cell proliferation and self-renewal." (PMID 33726836, 2021). "The results showed that the expression of EGFL8 was lower than EGFL6 and EGFL7 among all cancer types, wherein EGFL7 had the highest expression." (PMID 33391349, 2020). "A collation of 73 TEC marker genes from five studies showed that at most, only two cancer types shared one of these five genes (EGFL6, HEYL, MMP9, SPARC, PLXDC1), and the rest were expressed uniquely in only one cancer." (PMID 32375250, 2020). "EGFL6 is proved to relate to the progression of several cancers; however, the function and mechanism of EGFL6 in CRC has not yet been elucidated in detail." (PMID 33726836, 2021). "Several genes, such as EGFL6 (EGF Like Domain Multiple 6), COMP (Cartilage Oligomeric Matrix Protein), and SULF1 (Sulfatase 1), have been found to be related to multiple terms, and they are all research-proven cancer-related biomarkers." (PMID 35178071, 2021). "The results showed that EGFL6 and EGFL7 had a worse prognosis in these cancers." (PMID 33391349, 2020). "Although EGFL6 has been detected at the mRNA level in numerous cancers, the protein has not been detected in carcinoma cells and little is understood regarding its in vivo function." (PMID 26045973, 2014). "Also EGFL6 translation in MDA-MB-468 cells may have been disrupted, as protein production in cancer cells has been demonstrated to be aberrant." (PMID 26045973, 2014).
infection (1 paper, 2025). The state of being infected such as from the introduction of a foreign agent such as serum, vaccine, antigenic substance or organism. "EFEMP1 and LTBP4 were additionally downregulated at 12 hpi and 24 hpi following Delta infection, while EGFL6 and FBLN5 showed consistent downregulation at both time points in Omicron infection." (PMID 41200555, 2025).
metabolic disease (1 paper, 2022). A congenital disorder (due to inherited enzyme abnormality) or acquired (due to failure of a metabolically important organ) disorder resulting from an abnormal metabolic process. "In conclusion, we provide evidence for early alterations in AT gene expression related to AT dysfunction in children and identified EGFL6 as potentially being involved in processes underlying the pathogenesis of metabolic disease." (PMID 35457174, 2022). "Moreover, we identify EGFL6 as the gene most strongly positively associated with adipocyte hypertrophy and showed that its expression is related to early signs of AT dysfunction and metabolic disease, indicating a potential role in the pathogenesis of these processes." (PMID 35457174, 2022). "In children, EGFL6 expression was positively correlated to parameters of AT dysfunction and metabolic disease such as macrophage infiltration into AT, hs-CRP, leptin levels, and HOMA-IR." (PMID 35457174, 2022).
EGFL6 also shares sentences with these, for which no sentence is quoted: lung carcinoma (3 papers); gastric cancer (2); glioma (2); acoustic neuroma (1); bladder cancer (1); bone disorder (1); cavernous hemangioma (1); colorectal tumors (1); craniopharyngioma (1); leiomyoma (1); malignant lymphoma (1); neuroblastoma (1); osteoporosis (1); osteosarcoma (1); pancreatic carcinoma (1); pituitary adenomas (1); prostate carcinoma (1); rheumatoid arthritis (1); schwannoma (1); triple-negative breast carcinoma (1); type 2 diabetes (1).